IL18BP (interleukin 18 binding protein)
Diseases named in the same sentence as IL18BP in open-access papers (continued):
Sharing a sentence is not in itself a finding about the gene and the disease.
hyperferritinemia (1 paper, 2023). "Increased IL-8, IL-18BP, and sCD163 levels were causally associated with MAS; increased IL-8, MIP-1 alpha, M-CSF, and sCD25/IL-2Ra levels were causally associated with increased MCP-1/CCL2 levels; and increased IL-18BP and sCD163 levels were causally associated with hyperferritinemia." (PMID 37674218, 2023). "Our DAG analysis further identified causal associations between IL-18BP, sCD163, M-CSF, IL-8, MIP-1 alpha, and IL-2Ra/sCD25 with increased MCP-1/CCL2, MAS, and hyperferritinemia." (PMID 37674218, 2023).
hypertrophic cardiomyopathies (1 paper, 2012). "It would be interesting to further investigate potential differences in different cell types and to further elucidate the significance of c/EBPß dependent IL-18BP regulation in human tissues and diseases such as hypertrophic cardiomyopathies." (PMID 22761702, 2012).
IgG4-related diseases (1 paper, 2018). "AD displays a characteristic increase in IL-1Ra (not observed in other conditions), in sIL-1R1 (observed in IgG4-related diseases), in sIL-1R3 (as in SMC), in IL-18BP (observed in other diseases, but not in SMC or MCI that show a decrease), and in sIL-1R4." (PMID 30541566, 2018).
kidney stone (1 paper, 2025). "Five of these protein ratio pairs positively promote kidney stone development: BAIAP2/MME protein level ratio, GRPEL1/MME protein level ratio, HLAE/IL15 protein level ratio, CEACAM1/GGT1 protein level ratio and BTN2A1/IL18BP protein level ratio." (PMID 40673688, 2025).
liver disorder (1 paper, 2025). A disease involving the liver. "Interestingly, our present intrahepatic observations deepen previous works reporting elevated circulating levels of IL-18BP in patients with different types of chronic liver diseases, suggesting that IL-18BP could be an interesting serum biomarker to evaluate liver disorders progression." (PMID 41275524, 2025).
lupus nephritis (1 paper, 2025). Glomerulonephritis in the context of systemic lupus erythematosus. "Among 18 studies investigating IL-18 in lupus nephritis (LN), only three concurrently measured serum IL-18BP levels." (PMID 41142814, 2025).
melanoma (1 paper, 2023). A malignant, usually aggressive tumor composed of atypical, neoplastic melanocytes. "Furthermore, in vivo neutralization of IL-18 with IL-18BP reduced melanoma metastases into the liver in a mouse model and il18-/- mice exhibited less tumor growth in a multiple myeloma mouse models." (PMID 37298187, 2023).
mucinous carcinoma (1 paper, 2014). "However, while in the serous papillary carcinoma and mucinous carcinoma tissues the main IL-18BP expression was by epithelial tumor cells (resp)." (PMID 24963217, 2014).
multiple sclerosis (1 paper, 2024). A progressive autoimmune disorder affecting the central nervous system resulting in demyelination. "Clinical and preclinical studies have highlighted IL-18BP’s therapeutic relevance in conditions such as traumatic brain injury, multiple sclerosis, and systemic inflammatory disorders." (PMID 39858411, 2024).
nephritis (1 paper, 2018). Inflammation of renal tissue. "Additional evidence for the critical role of IL-18 is provided by multivariate analysis, which identified lower IL-18BP and higher sIL-1R4 as distinguishing features of patients with active nephritis." (PMID 29422069, 2018). "PLS identified sIL-1R4, sIL-1R2 and anti-dsDNA as variables distinguishing patients with active from those with inactive disease; sIL-1R4, IL-18BP and anti-dsDNA identified patients with active nephritis; sIL-1R4, C3, IL-18 and free IL-18 identified patients with haematological involvement." (PMID 29422069, 2018). "Variables identifying patients with active nephritis were sIL-1R4 (VIP = 1.849), IL-18BP (VIP = 1.605), and anti-dsDNA (VIP = 1.524)." (PMID 29422069, 2018).
neuropathy (1 paper, 2021). A disorder affecting the nervous system that manifests with pain, tingling, numbness, and/or muscle weakness. "Our previous results show that inhibition of their actions by the administration of an IL-1 receptor antagonist (IL-1RA) and IL-18 binding protein (IL-18BP) alleviates the symptoms of neuropathic pain and enhances the analgesic effect of opioids on neuropathy." (PMID 34681732, 2021).
pancreatic tumor (1 paper, 2023). "An earlier study had shown that NF-κB-dependent expression of IL-18 by human and murine pancreatic tumor cells increased their proliferation and invasion in vitro and in vivo, and they were blocked in the presence of IL-18BP." (PMID 37298187, 2023).
plaque psoriasis (1 paper, 2014). "A clinical preparation of human IL-18BP has been shown to be safe and effective in patients with RA or plaque psoriasis." (PMID 24926998, 2014).
psychosis (1 paper, 2021). "Our results were similar to the previous clinical report that both levels of IL-18 and IL-18/IL-18BP ratios were significantly higher in patients with early-onset psychosis (EOP) aged 12–18 years than in age-matched healthy controls." (PMID 33441182, 2021).
pulmonary tuberculosis (1 paper, 2020). A bacterial infection that affects the lungs and is caused by Mycobacterium tuberculosis. "This work aims to assess the level of expression of IL-18, IL-18BP, IL-18R, as well as IFN-γand IL-37 genes in patients with active pulmonary tuberculosis (ATB), healthy individuals with latent M.tb infection (LTB), and healthy uninfected controls (Control)." (PMID 32521630, 2020). "The role of IL-18, its binding protein IL-18BP, and IFN-γ in the development of the immune response against mycobacteria was confirmed by observing the increased level of the expression of these genes in the group of patients with active pulmonary TB." (PMID 32521630, 2020).
sarcopenia (1 paper, 2026). Progressive decline in muscle mass due to aging which results in decreased functional capacity of muscles. "In conclusion, we have found that IL-18BP associates negatively with physical performance under basal conditions in patients about to undergo surgery and in older individuals with sarcopenia." (PMID 41592067, 2026). "This analysis showed that consistent with the analysis of the sarcopenia cohort, in men IL-18BP negatively associated with QMVC, there were too few women in this study to support analysis." (PMID 41592067, 2026). "One strength of our data is that we have identified the same association (IL-18BP inversely associating with strength) in two completely different cohorts, those about to undergo surgery and older individuals with sarcopenia." (PMID 41592067, 2026). "As activation of AMPK promotes mitochondriogenesis, such an effect would be consistent with the negative association we see between IL-18BP, physical performance in both cohorts and the mitochondrial gene expression in the acute sarcopenia cohort." (PMID 41592067, 2026). "Therefore, to determine whether the same would be true in patients with clinically relevant, chronic sarcopenia, we quantified IL-18BP in the plasma of patients enrolled in the LACE clinical trial by ELISA and compared it with physical performance at baseline, and after 6 and 12 months of the trial." (PMID 41592067, 2026).
schizophrenia (1 paper, 2012). A major psychotic disorder characterized by abnormalities in the perception or expression of reality. "In particular, the elevated levels of IL-18BP, likely a consequence of the body’s attempt to counteract the early prominent inflammation which characterizes schizophrenia, are maintained in earlier and later stages of the disease." (PMID 22913567, 2012). "We analyzed 77 patients with schizophrenia diagnosis (SCZ) and 77 healthy control subjects (HC) for serum concentration of both IL-18 and its natural inhibitor, the IL-18 binding protein (IL-18BP)." (PMID 22913567, 2012).
Sjögren’s Syndrome (1 paper, 2025). "The objective of this study was to explore the expression profile of the Interleukin (IL)-37/IL-18/IL-18BP/IL-18R axis in patients with primary Sjögren’s syndrome (pSS)." (PMID 40430016, 2025). "This study aims to explore the contribution of the IL-37/IL-18/IL-18BP/IL-18R signaling axis to the immunopathogenesis of primary Sjögren’s syndrome, with a focus on its local and systemic expression profiles." (PMID 40430016, 2025).
tuberculosis (1 paper, 2020). A chronic, recurrent infection caused by the bacterium Mycobacterium tuberculosis. "The study was aimed to assess IL-18, IL-18 binding protein (IL-18BP), IL-18R, IFN-γ, and IL-37 mRNA expression in patients with active tuberculosis (ATB) and healthy volunteers with latent M.tb-infection (LTB) or M.tb-uninfected healthy controls (Control)." (PMID 32521630, 2020). "In ATB, but not LTB individuals, the overexpression of IL-18 and IL-18BP, as well as a significant increase in IFN-γ mRNA expression, might be considered as a manifestation of active tuberculosis disease." (PMID 32521630, 2020).
tubular carcinoma (1 paper, 2025). "The IL‐18/IL‐18BP ratio was significantly higher in the tubular carcinoma and PDAC cases compared to the intestinal‐type carcinomas." (PMID 39969214, 2025).
type 2 diabetes (1 paper, 2025). "The levels of both IL-18 and IL-18BP were shown to be changed in type 2 diabetes in a recent study." (PMID 41465472, 2025). "Only seven genes had the same direction of effect for comparison of type 2 diabetes samples and healthy samples in all eight datasets: LOC112268118 and MPO had positive logFC, and IL18BP, DELE1, TSPAN32, ITFG2, and NISCH all had negative logFC." (PMID 41465472, 2025).
tumor (23 papers, 2015 to 2025). "Higher IL18BP expression in ccRCC was also associated with higher tumor grade, higher hypoxia signatures scores, and worse survival." (PMID 39561007, 2024). "The IL-18 fusion resisted interleukin-18 binding protein (IL-18BP) inhibition and exhibited a 10,000-fold reduction in activity while preserving cis-signaling and demonstrated strong efficacy across tumor models." (PMID 41488627, 2025). "WTX-518, an IL-18 pro-drug resistant to IL-18BP inhibition, is conditionally activated within the tumor microenvironment, promotes increased influx and activation of NK cells and polyfunctional CD8 T cells, and induces regressions in mouse tumor models." (PMID 39769266, 2024). "Using pantumor transcriptomic data, we found that clear cell RCC had among the highest expression of IL-18 receptor subunits and IL18BP of tumor types in the database." (PMID 39561007, 2024). "To assess the functional impact of IL18 in PDA, we blocked IL18 using IL18-binding protein (IL18BP) in a patient-derived model using tumor bioprints." (PMID 36131941, 2022). "IL-35 regulated the tumor microenvironment together with negative regulators (e.g., IL-18BP and IL-10), which played a key role in tumor immune escape, and promoted tumor progression and metastasis." (PMID 33777929, 2021). "To further explore the correlations between tumor infiltrated immune cells and IL18BP, we used the CIBERSORT algorithm for immune cell quantization." (PMID 33469515, 2020). "In the GEO dataset GSE15459, patients with high IL18BP levels in tumor samples tended to have poorer survival outcomes compared with those with lower IL18BP levels." (PMID 33469515, 2020). "We took both the IL18BP gene expression and the fraction of tumor-infiltrating immune cells into consideration." (PMID 33469515, 2020). "Meanwhile, the apoptosis and proliferation status in the orthotopic implantation tumor was measured and it was found that the tumor tissue showed more apoptosis and decreased proliferation in mice treated with IL-18BP+PPI." (PMID 29599908, 2018). "The results showed that mice treated with IL-18BP+PPI had smaller tumor size, healthier livers, and fewer liver metastases than mice injected with PBS." (PMID 29599908, 2018). "IL-18 and IL-18BP were expressed in epithelial cells of both tumor and normal ovarian tissues." (PMID 41561739, 2025). "Therefore, we evaluated RMP-IL-18mutE4 alongside an anti-mouse IL-18BP antibody in the aggressive MC38i tumor model." (PMID 41488627, 2025). "In patients that are resistant to checkpoint immunotherapy, targeting IL-18BP could release IL-18 from its complex, enabling it to exert its beneficial anti-tumor effects." (PMID 39769266, 2024). "Moreover, in a nonoverlapping RCC patient cohort, we observed an increase in tumor IL-18BP protein levels by qIF, indicating that this is both a systemic and local phenomenon." (PMID 39561007, 2024). "Moreover, tumor-derived IL-18BP is an immune checkpoint molecule that inhibits IL-18 mediated anti-tumor activity in mouse and human tumors." (PMID 36032110, 2022). "The integration of IL18BP and tumor-infiltrating CD4+ T cells could be a potential target for STAD therapy." (PMID 33469515, 2020). "Consequently, the authors designed DR-18, an IL-18 resistant to IL-18BP inhibition, which enhances tumor regression." (PMID 33261061, 2020). "Taken together, these studies highlight the fact that IL-18 may improve immunotherapy only in some cases, and that it depends on the tumor immune-infiltrating cells and their capacity to secrete inhibitory molecules, such as IL-18BP." (PMID 33261061, 2020). "The results suggest that lower UBB and IL-18BP expression may be associated with higher MET and lower CNV levels; evaluating the expression of these genes might therefore aid in early tumor diagnosis and prognosis." (PMID 31257224, 2019).
tumor (continued). "In addition, interactions between IL18, which is an immunity-enhancing cytokine, and IL18BP at the cell surface result in anti-tumor effects, including stimulation of T cell proliferation and increases in natural killer cell activity." (PMID 31257224, 2019). "However, IL-18 became incompetent by RNAi interference or the application of IL-18 binding protein (IL-18BP), which activated NK cells to inhibit tumor growth." (PMID 29312552, 2017). "Therefore, this study investigated the protein expression of NLRP3, ASC, caspase‐1, IL‐1B, IL‐18, IL‐1RA, and IL‐18BP on tumor cells by utilizing multiplexed immunohistochemistry on PDAC and IPMN samples, examining their association with pathological features and prognoses." (PMID 39969214, 2025). "Importantly, combined treatment with IL-18BP and doxorubicin significantly increased macrophage infiltration and activated macrophages with M1-polarity compared to single treatment and resulted in significantly inhibition of tumor growth." (PMID 36274066, 2022). "As immunosuppressive molecules (e.g., PD‐L1, IDO1, and IL‐18BP) that can be induced by interferon‐gamma (IFN‐γ) are generally important to facilitate immune evasion by tumor cells, we wondered whether the expression of these immunosuppressive molecules in NPC cells is affected by CBX1." (PMID 36310139, 2022). "Thus, we hypothesized that IL18BP might influence STAD prognosis through the integration of tumor infiltrated immune cells." (PMID 33469515, 2020). "Depletion of IL-18 expression in macrophage showed similar effects with IL-18BP treatment on HOS and SJSA-1 tumor cells." (PMID 36274066, 2022). "To further study the IL18BP protein expression, we performed immunohistochemistry staining of 12 STAD tumor samples and normal solid tissues." (PMID 33469515, 2020). "In samples from patients with RCC treated with immune checkpoint inhibitors, IL-18BP protein expression increased in the tumor microenvironment and in circulation within plasma in nonresponding patients, and it decreased in the majority of responding patients." (PMID 39561007, 2024). "Interestingly, STAT1 increases the expression of interleukin-18 binding protein (IL-18BP) and indoleamine 2,3-dioxygenase (IDO), an immunosuppressive enzyme that suppresses anti-tumor immunity." (PMID 33834023, 2021). "Moreover, combined treatment with IL-18BP and a PPI significantly repressed tumor growth and metastasis in the PC orthotopic implantation model." (PMID 29599908, 2018). "Furthermore, knocking down of IL18R1 in HOS and SJSA-1 cells showed similar effects with IL-18BP treatment on suppressing CD47 expression, enhancing macrophage infiltration and activation and inhibiting tumor growth." (PMID 36274066, 2022). "IL-18BP is expressed in primary EOC and tumor-associated leukocytes in vivo, but not in human EOC cell lines, where it may be induced by stimulation with IFN-γ or IL-27." (PMID 26657115, 2015). "In our studies, although IL-18 levels were higher in serum and tumor of IMSA101-treated mice, we did not observe differences in IL-18BP levels between cohorts receiving IMSA101 and CART, either alone or in combination." (PMID 38730243, 2024).